TTC13 (tetratricopeptide repeat domain 13)
Synonyms: FLJ22584
Tractability: PROTAC: ubiquitination databases record sites on it; its protein half-life has been measured.
Gene: Protein-coding gene on chromosome 1 (230,902,945 to 230,978,893, reverse strand). Ensembl gene ENSG00000143643.
Subcellular location (Human Protein Atlas): Nucleoplasm
Genetic constraint (gnomAD): Loss-of-function variants: 37 observed, 71.64 expected, observed/expected ratio (o/e) 0.52, 90% interval 0.4 to 0.68. The upper end of that interval is the gene's LOEUF score, 0.68, which puts it in group 2 of 6, group 1 being the genes least tolerant of losing a copy. Missense variants: 565 observed, 712.24 expected, observed/expected ratio (o/e) 0.79, 90% interval 0.74 to 0.85. Synonymous variants: 270 observed, 266.07 expected, observed/expected ratio (o/e) 1.01, 90% interval 0.92 to 1.12.
Homologues: Orthologues: chimpanzee TTC13 (99% identical), rabbit TTC13 (99% identical), pig TTC13 (98% identical), dog TTC13 (98% identical), macaque TTC13 (97% identical), guinea pig TTC13 (94% identical), mouse Ttc13 (93% identical), rat Ttc13 (89% identical), tropical clawed frog ttc13 (79% identical), zebrafish ttc13 (74% identical), Drosophila melanogaster Tmtc4 (11% identical), Caenorhabditis elegans ttc-7 (8% identical). Paralogues in human: CFAP70 (15% identical), TTC6 (14% identical), OGT (12% identical), TTC7B (9% identical), TTC7A (9% identical), TTC8 (9% identical), TTC34 (9% identical), TMTC1 (8% identical), TMTC2 (8% identical), TMTC3 (8% identical), TMTC4 (8% identical), IFT88 (8% identical), and 2 more.
Diseases named in the same sentence as TTC13 in open-access papers:
TTC13 is named in the same sentence as 8 diseases in open-access papers, as found by Europe PMC text mining. Sharing a sentence is not in itself a finding about the gene and the disease. The quoted sentences say what the papers report.
autism (1 paper, 2021). Persistent deficits in social interaction and communication and interaction as well as a markedly restricted repertoire of activity and interest as well as repetitive patterns of behavior. "To further determine whether these predicted proteins were associated with ASD, we compared their corresponding genes with autism-related genes listed in the AutismKB and found that 55 genes were reported associated with ASD except TTC13, RARS, THOC5, and ATPAF1." (PMID 33716802, 2021).
breast carcinoma (1 paper, 2014). "For Breast cancer 6 genes had significant aCGH/expression correlation at a level of 0.05 in all 7 breast cancer data sets (BCL9, AZIN1, TAF2, YTHDF1, TTC13, FBXL20)." (PMID 25148247, 2014).
gastric cancer (1 paper, 2023). A primary or metastatic malignant neoplasm involving the stomach. "Although the role of TPR-related proteins in tumors has been reported in leukemia, liver cancer, and gastric cancer, the function of TTC13 in tumors is not clear, and the expression and biological functions of TTC13 in ccRCC need to be determined." (PMID 37927783, 2023).
renal carcinoma (1 paper, 2023). A carcinoma arising from the epithelium of the renal parenchyma or the renal pelvis. "Conversely, TTC13 overexpression resulted in the opposite effects, suggesting that TTC13 was involved in the regulation of renal cancer cell survival and autophagy." (PMID 37927783, 2023).
tumor (1 paper, 2023). "Collectively, these findings indicated that TTC13 may be associated with suppressed antitumor immune responses in the tumor microenvironment of ccRCC." (PMID 37927783, 2023). "Together, these results indicated that knockdown of TTC13 effectively inhibited tumor growth in vivo." (PMID 37927783, 2023). "Consistently, qRT-PCR analysis (tumor =64, normal =64) showed that the mRNA level of TTC13 was significantly higher in ccRCC tissues than in normal tissues (P < 0.001) which was further confirmed by western blotting and IHC." (PMID 37927783, 2023). "To explore the effect of TTC13 on tumor growth in vivo, we subcutaneously injected 786-0 cells transfected with either TTC13 NC or shRNA plasmid into nude mice and found that the tumor volume and weight of the shRNA group were evidently smaller than that of the NC group." (PMID 37927783, 2023). "Specifically, we experimentally determined whether Wnt/β-catenin and IL6-JAK-STAT3 signal pathways were activated in ccRCC by examining the expression of TTC13, β-catenin, JAK2, p-STAT3, STAT3 and p-JAK2 in ccRCC tumor tissues as well as the adjacent normal tissues." (PMID 37927783, 2023). "The expression level of TTC13 was different between various tumors and normal tissues with a significant upregulation in ccRCC (P < 0.001), which was supported by the data from the paired tumor and non-cancerous samples." (PMID 37927783, 2023). "Therefore, therapies targeting TTC13 as well as IL6-JAK-STAT3 signaling pathway may benefit ccRCC patients by simultaneously suppressing tumor cell growth and stimulating anti-tumor immunity." (PMID 37927783, 2023).
TTC13 also shares sentences with these, for which no sentence is quoted: breast tumor (1 paper); leukemia (1); liver cancer (1).